HP (haptoglobin)
Diseases named in the same sentence as HP in open-access papers (continued):
Sharing a sentence is not in itself a finding about the gene and the disease.
kidney disease (11 papers, 2011 to 2025). "The comparative analysis involving CKD and HV groups showed a differential accumulation of α-1-microglobulin, apolipoprotein A-IV, γ-fibrinogen and haptoglobin in patients with kidney disease." (PMID 21569504, 2011). "Red blood cell and haptoglobin transfusions may prevent fatal hemolytic anemia, renal disorder, embolism, and systemic complications." (PMID 39877320, 2025). "Red blood cell and haptoglobin transfusions may prevent fatal hemolytic anemia, renal disorders, embolism, and systemic complications." (PMID 39877320, 2025). "In another study, proteomic analysis identified haptoglobin as a candidate biomarker for predicting early decline in renal function, and the ratio of haptoglobin to creatinine has the ability to predict renal function in diabetic patients who have not yet exhibited significant renal disease." (PMID 36425298, 2022).
metabolic disease (7 papers, 2013 to 2025). A congenital disorder (due to inherited enzyme abnormality) or acquired (due to failure of a metabolically important organ) disorder resulting from an abnormal metabolic process. "Evaluating the haptoglobin concentration in cases of uterine and metabolic diseases also has diagnostic and prognostic importance." (PMID 40492724, 2025). "Serum interleukin-1, interleukin-6, tumor necrosis factor, haptoglobin, serum amyloid A and lactate were increased in cows with metabolic diseases from −8 and −4 weeks before calving, as well as during and after diagnosis of the disease." (PMID 30889779, 2019). "Obese and overweight prepubertal children have elevated serum levels of IL-6, and haptoglobin and TGF-β1 which are known as markers of inflammation that may increase the cardiovascular and/or metabolic disease risk." (PMID 27275205, 2015).
immune diseases (5 papers, 2013 to 2024). "Interestingly, certain haptoglobin phenotypes have been associated with an increased risk of inflammation and cardiovascular and auto-immune disease." (PMID 39000133, 2024). "Acute phase proteins (APPs) such as C-reactive protein (CRP), haptoglobin (HP) and serum amyloid A (SAA) were secreted by hepatocytes and served as a crucial role in the etiopathogenesis of immune diseases." (PMID 36932457, 2023).
heart disease (4 papers, 2014 to 2022). "For example, it has been shown that the incidence of acute episodes of ischaemic heart disease increases in patients with some haptoglobin allotypes or HLA antigens." (PMID 35305618, 2022). "Through big data analysis, we found that HBP family members, such as HP, CXCL12, COL3A1, PECAM1, and other highly correlated genes, play a role in heart diseases." (PMID 32612856, 2020).
neurological diseases (3 papers, 2017 to 2023). "It has been shown that dysregulation of haptoglobin (Hpt) in cerebrospinal fluid can reflect neurological diseases." (PMID 37299978, 2023). "Expression alterations of APOA4, HP, and C3 proteins in OCD profile were also mentioned in other neurological diseases." (PMID 29158881, 2017).
inflammation (2 papers, 2021). Aberrant reaction of the microcirculation characterized by movement of fluid and leukocytes from the blood into extravascular tissues. "Systemic inflammation is typically characterized by elevations in the levels of acute phase proteins, including C-reactive protein (CRP), apha-2 macroglobulin (a2M), haptoglobin (Hp) and serum amyloid P (SAP)." (PMID 34867953, 2021).
benign tumours (1 paper, 2019). "The concentration of haptoglobin was significantly raised in ES and LS-EOC compared with benign tumours." (PMID 31315664, 2019).
HP also shares sentences with these, for which no sentence is quoted: acute myocardial infarction (5 papers); hematologic disease (4); hepatitis C (4); leukocytosis (4); liver (4); liver cirrhosis (4); meningioma (4); Non-Alcoholic Fatty Liver Disease (4); systemic inflammatory response syndrome (4); chronic gastritis (3); chronic periodontitis (3); colon carcinoma (3); Crohn disease (3); G6PD deficiency (3); gastrointestinal infections (3); hemochromatosis (3); liver failure (3); renal dysfunction (3); small cell lung carcinoma (3); ulcerative colitis (3); viral diseases (3); adenocarcinoma (2); border disease (2); breast tumor (2); chronic graft versus host disease (2); chronic hepatitis B (2); Cobalamin deficiency (2); coronary atherosclerosis (2); diabetic retinopathy (2); endocarditis (2).
A further 161 diseases each share a sentence with HP in 2 papers or fewer.